INS (insulin)
Diseases named in the same sentence as INS in open-access papers (continued):
Sharing a sentence is not in itself a finding about the gene and the disease.
Hypoglycemia (continued). "AAV-mediated Aspg restoration in the LKO mice livers abolished all the metabolic benefits accomplished by the deficiency of Aspg, including improved glucose tolerance, hypoglycemia and high insulin levels after meals." (PMID 40760121, 2025). "A nurse called P51 mid-evening because the patient’s blood glucose had become moderately high, in response to which P51 prescribed a smaller insulin dose than the one that had earlier caused hypoglycaemia." (PMID 40973362, 2025). "Multiple studies have indicated that intensive insulin therapy is associated with a higher risk of hypoglycemia." (PMID 40901501, 2025). "An individualized approach to timing and selection of insulin therapy is essential for optimizing glycemic control and minimizing hypoglycemia risk." (PMID 40190894, 2025). "While hypoglycemia risk is highest in diabetic patients on insulin or sulfonylureas, profound caloric restriction, starvation ketosis, and overdose can precipitate hypoglycemia in non-diabetic individuals as well." (PMID 41368024, 2025). "Some benefits of SGLT2i use include their non-insulin-dependent antidiabetic effects, resulting in a low risk of hypoglycemia." (PMID 41009577, 2025). "Risk of hypoglycemia is increased with concurrent use of other insulin agents as well as insulin secretagogues." (PMID 40156735, 2025). "Regarding the risk of hypoglycemia due to systemic absorption of topically applied insulin, blood glucose levels measured before and after the procedure showed no significant changes, indicating minimal systemic absorption." (PMID 39970082, 2025). "Insulinomas are located in the pancreas and secrete insulin, causing a syndrome characterized by symptoms of hypoglycemia." (PMID 40406452, 2025). "While the risk of hypoglycemia is low when used alone, the risk increases when combined with sulfonylureas or insulin." (PMID 41041641, 2025). "Elderly diabetic patients are at a heightened risk for severe hypoglycemia, and insulin pumps significantly enhance the safety of insulin therapy." (PMID 41180388, 2025). "Current usage patterns show NPH insulin is primarily used in resource-limited settings due to its lower cost, though its variably absorption and peak effect at 4–6 hours can increase hypoglycemia risk compared to more recent analogs." (PMID 41531706, 2025). "Congenital Hyperinsulinism (CHI) is a rare genetic disorder of the pancreatic β-cells known to cause recurring episodes of hypoglycaemia due to dysregulated insulin secretion, leading to dangerously low blood glucose concentrations in infants and children." (PMID 40265383, 2025). "Included studies addressed diverse AI applications, including glucose prediction, hypoglycemia risk assessment, and insulin dosing optimization." (PMID 40895926, 2025). "The risk of hypoglycemia was higher with the SGLT2i/DPP4i combination only when insulin or sulfonylureas were used as background therapy." (PMID 40342458, 2025). "We found that NT5C1A/NT5C2 double-knockout (NT5C-dKO) mice exhibited mild hypoglycemia, associated with enhanced skeletal muscle insulin action and reduced hepatic glucose production." (PMID 39947478, 2025). "If suspecting endogenous hyperinsulinemia, a supervised fast can be performed to differentiate between these causes by checking insulin, C-peptide, proinsulin, and β-hydroxybutyrate levels during fasting hypoglycemia and screening for oral hypoglycemic agents." (PMID 40083398, 2025). "It has previously been reported that insulin most likely causes hypoglycemia among all diabetic drugs." (PMID 40777704, 2025). "Non-physiologic route of administration, the continuous risk of hypoglycemia, accessibility to insulin, the cumbersome nature of the technologies, and the overall cost of disease management has driven the search for alternative therapies." (PMID 41289263, 2025). "Short-acting insulin, given before meals, should be considered in patients who have erratic eating habits to reduce hypoglycaemia risk." (PMID 40863223, 2025).
Hypoglycemia (continued). "Insulin treatment is associated with an increased risk of hypoglycemia, which is compounded in people of older age, but the risk is lower with longer-acting vs intermediate- or long-acting basal insulin analogs." (PMID 40309264, 2025). "Congenital hyperinsulinism (HI) is characterized by inappropriate insulin secretion from the pancreatic beta-cells which causes severe hypoglycemia." (PMID 40041288, 2025). "Few studies also reported that a lack of knowledge on insulin self-administration and taking a higher average daily dose of insulin were factors associated with hypoglycemia." (PMID 40110390, 2025). "The educational intervention helped to reduce the fear of insulin therapy and its perceived risk of causing hypoglycemia." (PMID 40290070, 2025). "These risk factors include lifelong insulin therapy, hypoglycemia fear, and social discomfort to have insulin injections in the presence of the others, food preoccupation (e.g., carbohydrate counting), low self-esteem, and depression." (PMID 40163174, 2025). "Specifically, an increased Charlson index, lower BMI, reduced C-peptide levels, decreased TG, elevated HbA1c, elevated creatinine levels, and insulin use were linked to a higher risk of hypoglycemia." (PMID 41040859, 2025). "The risk of hypoglycemia was higher with SGLT2i/DPP4i when insulin or sulfonylureas were used as background therapy." (PMID 40342458, 2025). "As blood glucose decreases after meals, insulin-IAA complexes dissociate, releasing large amounts of active insulin and predisposing patients to hypoglycemia." (PMID 41585798, 2025). "These advantages contribute to a lower risk of nocturnal hypoglycemia in individuals with T1D when compared to NPH insulin." (PMID 40574081, 2025). "Most insulinomas are sporadic, solitary, and benign, yet they are associated with life-threatening hypoglycemia due to autonomous insulin secretion." (PMID 40375949, 2025). "iGlarLixi has also demonstrated improved glycaemic control, weight benefit and reduced risk of hypoglycaemia versus the premixed insulin, biphasic insulin aspart 30/70 (BIAsp 30), in people with T2D suboptimally controlled on basal insulin plus OADs." (PMID 40176458, 2025). "The multivariable logistic regression analysis showed a significant association between a low level of knowledge regarding insulin self-administration and the high prevalence of self-reported hypoglycemia." (PMID 40110390, 2025). "Heparin seemed to ameliorate insulin efficiency by destroying NETs; therefore, heparin-warfarin treatment caused hypoglycemia one or two weeks after the start of heparin-warfarin treatment, and we needed to decrease the number of DM medications." (PMID 41158717, 2025). "When used alone or in combination with metformin, semaglutide has an inherently low hypoglycemia risk, but this increases when used with insulin or with insulin secretagogues such as sulfonylureas." (PMID 41302309, 2025). "Pre-exercise, a blend paired with fat, fiber, and carbohydrates can provide steadier glucose and amino acid delivery, reducing hypoglycemia risk in insulin-treated athletes." (PMID 41305580, 2025). "In terms of safety, SGLT2 inhibitors are generally well tolerated, with a low intrinsic risk of hypoglycemia when used as monotherapy because of their insulin-independent mechanism of action." (PMID 41471118, 2025). "The self-limiting action that is controlled by plasma glucose levels minimizes the risk of hypoglycemia by acting independently of insulin action." (PMID 40872492, 2025). "Hypoglycemia risk is heightened in individuals using insulin or insulin secretagogues, particularly in situations of mismatched insulin action and energy expenditure." (PMID 41030722, 2025). "Compared with insulin administration, treatment with leptin is associated with a lower risk of hypoglycemia, directly inhibits fat synthesis and is an effective treatment for ketoacidosis, a life-threatening complication of T1DM." (PMID 40429740, 2025).
Hypoglycemia (continued). "This high-dose insulin therapy is associated with hypoglycemia and hypokalemia, requiring strict blood glucose and potassium monitoring along with supplemental glucose and potassium administration." (PMID 41141045, 2025). "Similar to GLP-1 RAs, SGLT2 inhibitors are associated with a low risk of hypoglycemia, which is clinically relevant only when combined with insulin or insulin secretagogues." (PMID 41301689, 2025). "This potentially puts patients receiving insulin infusions at a risk of hypoglycaemia between measures." (PMID 41146739, 2025). "These agents are especially attractive as additional therapies because they boost insulin release based on glucose levels, reducing the risk of hypoglycemia." (PMID 40671916, 2025). "An individualized approach to timing and selection of insulin therapy, considering patient’s choice, age, comorbidity and glycaemic profile, is essential for optimizing glycemic control and minimizing hypoglycemia risk." (PMID 40190894, 2025). "The process boosts glucose-dependent insulin production while reducing glucagon release from the pancreatic α-cells, resulting in decreased blood sugar levels and a minimized risk of hypoglycemia because of increased insulin and decreased glucagon secretion." (PMID 40422559, 2025). "Regarding antidiabetic therapy, sulfonylureas and insulin have been associated in previous studies with an increased risk of myocardial injury due to hypoglycemia." (PMID 41384191, 2025). "Most patients with hypoglycemia in our study were on sulfonylureas, which raise insulin levels independently of blood glucose, thereby increasing the risk of hypoglycemia." (PMID 40893590, 2025). "This error caused the patient to receive a dose of insulin, leading to severe hypoglycemia that required hospital intervention." (PMID 41473654, 2025). "For blood glucose levels below 140 mg/dL, the insulin infusion rate was reduced by 0.3 units per hour to minimize the risk of hypoglycemia." (PMID 39931500, 2025). "Our finding that insulin treatment prior to 36 weeks PMA was significantly associated with longer time spent in hypoglycemia needs confirmation in future studies as well." (PMID 40576801, 2025). "Congenital Hyperinsulinism (HI) is a rare disease that causes severe and recurrent hypoglycemia due to dysregulated insulin secretion." (PMID 40385354, 2025). "The significant association between insulin use and hypoglycemia underscores the importance of careful management and monitoring of insulin therapy to reduce the risk of hypoglycemic episodes in this population." (PMID 41393767, 2025). "The clinical use of DWP16001 should include careful glucose monitoring and individualized insulin adjustments to mitigate the risk of hypoglycemia." (PMID 40796840, 2025). "A possible cause of his death was the inadequate management of insulin therapy in the out-of-hospital setting, as, despite having an indication for a single daily dose, the patient was readmitted with severe hypoglycemia." (PMID 41557551, 2025). "Recent studies show that 5 units of regular insulin with the same glucose volume is equally effective and reduces hypoglycemia risk." (PMID 40705102, 2025). "On the other hand, renal impairment in patients with DN leads to decreased insulin clearance, predisposing them to hypoglycemia." (PMID 41427046, 2025). "For patients with a history of hypoglycemia or those at higher risk of nocturnal episodes, clinicians should exercise caution when considering a once‐weekly insulin regimen." (PMID 40186384, 2025). "Modern AID systems reduce the risk of hypoglycemia by suspending basal insulin infusion and delivering automated correction boluses." (PMID 41156539, 2025). "At the end of the study, HbA1c was lower with iGlarLixi (7.3%) vs. premixed insulin (7.5%), with lower body weight and a reduced risk for hypoglycaemia." (PMID 40678871, 2025).
Hypoglycemia (continued). "Preliminary assessment excluded common causes of hypoglycemia, including exogenous insulin or sulfonylurea administration, insulinoma, autoimmune hypoglycemia, adrenal insufficiency, and hepatic or renal dysfunction." (PMID 41333493, 2025). "AKA management primarily focuses on fluid resuscitation with dextrose-containing fluids to suppress ketogenesis and thiamine repletion with specific avoidance of insulin due to the risk of inducing hypoglycemia." (PMID 41393585, 2025). "Insulin therapy has also been implicated in higher fracture incidence, predominantly through the risk of hypoglycaemia-induced falls." (PMID 41373586, 2025). "Considering the additional HTN influence of DM on cognitive decline, hypoglycemia, which is most often associated with the use of insulin or sulfonylureas, mainly affects patients with the worst glycemic stabilization and the most profound cognitive decline." (PMID 41295439, 2025). "Its insulin-independent mechanism reduces glycemic variability and the risk of hypoglycemia, while providing cardiovascular and renal protection." (PMID 41585798, 2025). "Clinical trials of dual-hormone systems have consistently demonstrated that adding glucagon reduces the incidence of hypoglycaemia compared with insulin-only systems, particularly in high-risk or high-activity scenarios such as exercise and overnight periods." (PMID 40718205, 2025). "Blood glucose should be monitored hourly for 4–6 h after glucose–insulin therapy due to hypoglycemia risk, which is more common in patients with kidney impairment, no diabetes, low baseline glucose, low body weight, or female sex." (PMID 40705102, 2025). "Findings suggested that IDegAsp presents a lower risk of hypoglycemia for patients requiring insulin during Ramadan and beyond." (PMID 40303934, 2025). "Once‐weekly insulin was associated with a statistically significant increase in the incidence of level 1 nocturnal hypoglycemia (RR: 1.09 with 95% CI [1.04, 1.15], p = 0.0009) and level 2 nocturnal hypoglycemia (RR: 1.24 with 95% CI [1.10, 1.40], p = 0.0004)." (PMID 40186384, 2025). "GLP‐1RA offers several advantages over insulin therapy, including a lower risk of hypoglycaemia, significant weight loss and favourable effects on cardiovascular risk factors (including blood pressure and lipids) and cardiovascular and renal outcomes." (PMID 40277315, 2025). "Insulin therapy increased the risk of hypoglycemia in T1D patients but decreased the risk of late-diabetic sequelae by reducing the average blood glucose." (PMID 41049970, 2025). "It is essential to note that, due to the heightened risk of AKI and hypoglycaemia in liver transplant recipients, insulin dosing should be approached with greater caution than typically recommended in standard guidelines." (PMID 40931439, 2025). "Hypoglycemia caused by insulin overdose is a primary factor contributing to multi-organ damage and mortality, with hypoglycemic encephalopathy being the most severe manifestation." (PMID 40362391, 2025). "The mechanisms underlying hypoglycemia in TS are diverse, involving both insulin-dependent and insulin-independent pathways." (PMID 40992506, 2025). "The findings emphasize the need for tailored management strategies, particularly regarding insulin therapy, to mitigate the risk of hypoglycemia and improve patient outcomes." (PMID 41393767, 2025). "Clinically, the consequences of ADRs and DDIs are profound, with bleeding episodes linked to anticoagulant combinations, hypoglycemia associated with insulin or sulfonylureas, and nephrotoxicity from certain drug regimens in patients with renal impairment." (PMID 41450405, 2025). "Studies have shown that intensification of insulin therapy leads to episodes of hypoglycemia, which is associated with an increased risk of cardiovascular complications in this population, which increases the risk of sepsis." (PMID 40863575, 2025).
Hypoglycemia (continued). "DPP-4 inhibitors, metformin, and GLP-1 agonists are generally safer than sulphonylureas and insulin during fasting, with a lower risk of hypoglycemia." (PMID 40007804, 2025). "This reduces the risk of inefficient insulin secretion and protects against hyperinsulinemia as well as hypoglycemia." (PMID 39857741, 2025). "Insulin therapy should be used with caution because of the risk of hypoglycemia due to the impaired glucagon function inherent to Type 3c diabetes." (PMID 40143090, 2025). "This aligns with findings suggesting that overlapping metabolic vulnerabilities, such as impaired glycogen storage and altered insulin regulation, exacerbate hypoglycemia risk." (PMID 40862109, 2025). "Treatment with glucagon-like peptide-1 receptor agonists (GLP-1RAs) is associated with low hypoglycemia risk due to enhancement of insulin secretion that is glucose-dependent and preserved glucagon response to hypoglycemia." (PMID 40964167, 2025). "AI purposes spanned glucose prediction, hypoglycemia risk assessment, insulin dosing optimization, and disease progression forecasting." (PMID 40895926, 2025). "Prolonged treatment time is directly associated with the use of larger volumes of hydration and insulin, which can lead to the appearance of complications such as hypoglycemia and hypokalemia." (PMID 40037551, 2025). "The coadministration of basal insulin with oral glucose-lowering medications or GLP-1RAs poses a lower risk of hypoglycemia than basal-bolus therapy while retaining the efficiency of the latter in managing blood glucose levels." (PMID 40097434, 2025). "As we know, nanotechnology-based therapies have shown the ability to directly deliver insulin to target cells and thereby reduce the risk of hypoglycaemia and weight gain that are associated with conventional treatments." (PMID 40574088, 2025). "The first 12 weeks of insulin initiation is generally known as the titration phase, when the risk of hypoglycaemia is higher and can lead to early discontinuation of insulin therapy." (PMID 40190894, 2025). "Celiac enteropathy drives malabsorption that increases the risk of prandial insulin-glucose mismatch and hypoglycemia." (PMID 40990290, 2025). "This unique pharmacological approach minimizes the risk of fluctuations in insulin concentration, which is important for reducing the risk of hypoglycemia." (PMID 40574081, 2025). "the pooled studies were homogeneous (p = 0.66, I2 = 0%), and once‐weekly insulin was associated with a statistically significant increase in the rates of level 2 hypoglycemia (RR: 1.06 with 95% CI [1.01, 1.12], p = 0.01)." (PMID 40186384, 2025). "Guidelines for the use of continuous glucose monitors before, during, and after exercise in people with type 1 DM are also adjusted to the type, intensity, duration, and timing of exercise, the dose of insulin, and risk of hypoglycemia." (PMID 40612145, 2025). "A lower insulin dosage reduces the risk of hypoglycemia and mitigates weight gain associated with high insulin intake." (PMID 40620795, 2025). "This was shown to decrease the risk of hypoglycemia and more closely mimic the physiological insulin secretion." (PMID 41471078, 2025). "This technology has the potential to improve glycemic management, reduce hypoglycemia risk, and enhance patient quality of life by minimizing the need for frequent insulin injections and dose adjustments." (PMID 40217595, 2025). "Contrary to its minimal impact on insulin in humans, xylitol ingestion in dogs causes insulin release greater than an equivalent dose of glucose, causing severe hypoglycemia." (PMID 41194783, 2025). "Congenital Hyperinsulinism (CHI) is a rare genetic disorder of pancreatic β-cells causing hypoglycaemia in children due to abnormal insulin secretion." (PMID 40265383, 2025).